STXBP4 (syntaxin binding protein 4)
Description:
Plays a role in the translocation of transport vesicles from the cytoplasm to the plasma membrane. Inhibits the translocation of SLC2A4 from intracellular vesicles to the plasma membrane by STX4A binding and preventing the interaction between STX4A and VAMP2. Stimulation with insulin disrupts the interaction with STX4A, leading to increased levels of SLC2A4 at the plasma membrane. May also play a role in the regulation of insulin release by pancreatic beta cells after stimulation by glucose (By similarity).
Synonyms: Synip; MGC50337
Tractability: Antibody: the Human Protein Atlas places it where antibodies can reach. PROTAC: ubiquitination databases record sites on it.
Gene: Protein-coding gene on chromosome 17 (54,968,727 to 55,173,632, forward strand). Ensembl gene ENSG00000166263.
Subcellular location: Cytoplasm
Subcellular location (Human Protein Atlas): Plasma membrane; Cytosol
Gene Ontology:
Molecular function: protein binding; syntaxin binding
Biological process: DNA damage response; positive regulation of cell cycle G1/S phase transition; positive regulation of keratinocyte proliferation; protein stabilization; regulation of insulin secretion involved in cellular response to glucose stimulus; insulin receptor signaling pathway; regulation of transport; response to stress
Cellular component: extracellular exosome; cytoplasmic vesicle; cytoplasm; phagocytic vesicle
Genetic constraint (gnomAD): Loss-of-function variants: 29 observed, 38.06 expected, observed/expected ratio (o/e) 0.76, 90% interval 0.57 to 1.04. The upper end of that interval is the gene's LOEUF score, 1.04, which puts it in group 4 of 6, group 1 being the genes least tolerant of losing a copy. Missense variants: 420 observed, 433.21 expected, observed/expected ratio (o/e) 0.97, 90% interval 0.89 to 1.05. Synonymous variants: 130 observed, 152.88 expected, observed/expected ratio (o/e) 0.85, 90% interval 0.74 to 0.98.
Homologues: Orthologues: chimpanzee STXBP4 (99% identical), macaque STXBP4 (96% identical), pig STXBP4 (86% identical), dog STXBP4 (84% identical), rabbit STXBP4 (83% identical), guinea pig STXBP4 (79% identical), mouse Stxbp4 (77% identical), rat Stxbp4 (70% identical), tropical clawed frog stxbp4 (48% identical), zebrafish stxbp4 (43% identical), Caenorhabditis elegans frm-5.1 (7% identical), Caenorhabditis elegans frm-5.2 (7% identical). Paralogues in human: PATJ (14% identical), MPDZ (13% identical), LNX1 (13% identical), LNX2 (13% identical), FRMPD2 (11% identical).
Diseases named in the same sentence as STXBP4 in open-access papers:
STXBP4 is named in the same sentence as 8 diseases in open-access papers, as found by Europe PMC text mining. Sharing a sentence is not in itself a finding about the gene and the disease. The quoted sentences say what the papers report.
breast cancer (11 papers, 2011 to 2024). A primary or metastatic malignant neoplasm involving the breast. "One potential explanation for the association between STXBP4 and breast cancer risk is that it encodes syntaxin binding protein 4, a scaffold protein." (PMID 32115800, 2020). "Previous studies supported the link between rs6504950 (a SNP in STXBP4) and overall breast cancer risk." (PMID 32115800, 2020). "Consistent with this, TCGA eQTL studies in breast tumour tissues find the risk allele of top candidate breast cancer risk SNP, rs2787486, to be significantly associated with increased STXBP4 mRNA expression." (PMID 27600471, 2016). "It has also been hypothesized that the risk allele for the two top breast cancer candidate SNPs, rs2787486 and rs244353, affected gene expression of STXBP4 and CD4 memory cells." (PMID 32115800, 2020). "However, in TCGA multiple SNPs associate with expression of the shortest isoform of STXBP4 (uc010dcc) with the top breast cancer risk SNP, rs2787486 having a FDR corrected P = 4.0 × 10−8 (r2 = 0.06)." (PMID 27600471, 2016). "Similarly, two fewer amino acids in the sixth exon of the STXBP4 gene are associated with increased breast cancer risk." (PMID 26472073, 2015). "Data analysis of STXBP4/COX11 polymorphisms and breast cancer risk showed that alleles of COX11 (rs17817901, rs6504950) were positively associated with breast cancer risk." (PMID 39676279, 2024). "All four genes identified by PrediXcan only were located near breast cancer SNPs previously identified by GWAS11, and three genes (CASP8, ALS2CR12, and STXBP4) also were reported by prior breast cancer TWAS 15,32." (PMID 36690614, 2023). "In particular, LINC00511 has been shown to induce radio-resistance in breast cancer resulting in recurrence and progression by regulating STXBP4 expression via miR-185." (PMID 32698787, 2020). "For example, a 2014 study showed association between breast cancer risk and seven breast cancer susceptibility loci (FGFR2, TOX3, STXBP4, SLC4A7, LSP1, 2q35, and 5p12)." (PMID 30249004, 2018). "Of the candidate genes in the region, both COX11 and TOM1L1 are highly expressed in both the HMEC and MCF7 breast cancer cell lines, while STXBP4 shows much lower expression (detected by RNAseq in TCGA)." (PMID 27600471, 2016). "For some of the loci, such as STXBP4, SRGAP2D and RAD51L1, the breast cancer association is highly significant and thus the number of likely SNPs is relatively small." (PMID 26472073, 2015). "Additionally, the sponging effect of LINC00511 on miR-185 has been shown to be involved in breast cancer recurrence and radioresistance via regulation of STXBP4 expression." (PMID 37124625, 2023). "lncRNA LINC00511 also upregulated breast cancer radioresistance via miR-185/STXBP4 axis." (PMID 35600868, 2022). "eQTL analysis in breast tumour tissues in TCGA find the risk allele of top candidate breast cancer risk SNP, rs2787486, to be significantly associated with increased STXBP4 expression, but not with COX11." (PMID 27600471, 2016). "Two genes, STXBP4 and HIST2H2BA, were specifically associated with ER+ but not with ER− breast cancer." (PMID 32115800, 2020). "We identified two genes, STXBP4 and HIST2H2BA, associated with ER status, which were significantly associated only with ER+ but not ER− breast cancer." (PMID 32115800, 2020).
breast tumour (1 paper, 2016). "Expression studies in breast tumor tissues found SNP rs2787486 to be associated with increased STXBP4 expression, suggesting this may be a target gene of this locus." (PMID 27600471, 2016).
Insulin resistance (1 paper, 2023). Increased resistance towards insulin, that is, diminished effectiveness of insulin in reducing blood glucose levels. "STXBP4 phosphorylation is required for insulin-stimulated Glut4 translocation and glucose uptake, suggesting that defects in STXBP4 phosphorylation underlie insulin resistance." (PMID 37545519, 2023).
Obesity (1 paper, 2022). Accumulation of substantial excess body fat. "We also analyzed the expression of FBXW7, MBOAT2, STXBP4, SPARCL1, and UTS after SLFN12 overexpression because these are obesity-related genes." (PMID 36291149, 2022).
cancer (3 papers, 2020 to 2022). A tumor composed of atypical neoplastic, often pleomorphic cells that invade other tissues. "Stxbp4 plays a key role in insulin signaling and has oncogenic activity and implicated in different cancers." (PMID 35389339, 2022). "As the first step, we intend to elucidate the functional roles of the 4 molecules in cancer biology in the similar manner as we did to clarify the essential role of STXBP4." (PMID 35841085, 2022).
tumor (2 papers, 2020 to 2022). "STXBP4 can facilitate cell directional migration, which plays a role in tumor metastasis with an unknown mechanism." (PMID 35795065, 2022). "Reduction in TP63 (ΔNp63) expression by STXBP4 might ameliorate tumor resistance to the current drug treatments and prolong survival of LSCC patient." (PMID 32993587, 2020). "We previously found that Syntaxin Binding Protein 4 (STXBP4) plays a crucial role in lesion growth and, therefore, clinical outcomes in LSCC patients through regulation of tumor protein p63 (TP63) ubiquitination." (PMID 32993587, 2020).
STXBP4 also shares sentences with these, for which no sentence is quoted: bladder tumors (1 paper); lung squamous cell carcinoma (1).